ENSG00000267968 (novel transcript, antisense to KLK15)
Synonyms: KLK3e; LOC105372441
Gene: Long non-coding RNA gene on chromosome 19 (50,830,530 to 50,851,089, forward strand). Ensembl gene ENSG00000267968.
Diseases named in the same sentence as ENSG00000267968 in open-access papers:
ENSG00000267968 is named in the same sentence as 3 diseases in open-access papers, as found by Europe PMC text mining. Sharing a sentence is not in itself a finding about the gene and the disease.
ENSG00000267968 shares sentences with these, for which no sentence is quoted: prostate carcinoma (5 papers); colorectal cancer (1); tumour (1).